MPG (N-methylpurine DNA glycosylase)
Diseases named in the same sentence as MPG in open-access papers:
MPG is named in the same sentence as 38 diseases in open-access papers, as found by Europe PMC text mining. Sharing a sentence is not in itself a finding about the gene and the disease. The quoted sentences say what the papers report.
glioblastoma (12 papers, 2013 to 2025). The most malignant astrocytic tumor (WHO grade IV). "For example, the levels of MGMT and N-methylpurine DNA glycosylase (APNG) mRNA in exosomes derived from glioblastoma patients have been found to be associated with temozolomide resistance levels and treatment effectiveness." (PMID 37568620, 2023). "Nevertheless, our findings, showing that MPG may be associated with TMZ resistance in human glioblastoma cells, could encourage and enable further research related to development of new therapeutic approaches to TMZ resistance using the enzyme MPG as a possible target along with MGMT." (PMID 33335215, 2020). "Our findings suggest that not only is MGMT implicated in resistance to TMZ but MPG, the first enzyme in base excision repair processing, is also involved, supporting its potential role as a target in anti-resistance chemotherapy for astrocytoma and glioblastoma." (PMID 33335215, 2020). "MPG is often overexpressed in glioblastomas, and a correlation was shown between high MPG expression, TMZ resistance, and poor OS compared to patients lacking MPG (as measured by immunohistochemistry)." (PMID 38068493, 2023). "Subsequent enhanced nuclear localization of MPG increases the DNA repair capacity and contributes to treatment resistance in glioblastoma." (PMID 37491696, 2023). "MPG expression was also previously shown to predict temozolomide sensitivity in glioblastoma and ovarian cancer cell lines, but TMZ sensitivity in CRC was not previously addressed." (PMID 28903334, 2017). "Aberrant promoter methylation of HIV‐1 TAT‐interactive protein 2 (HTATIP2) attenuates the negative regulatory capacity of glioblastoma cells to reduce nuclear translocation of cancer‐relevant proteins such as the base excision repair enzyme N‐methylpurine DNA glycosylase (MPG)." (PMID 37491696, 2023). "Epigenetic silencing of HTATIP2 may thus increase nuclear localization of MPG, thereby enhancing the capacity of the glioblastoma cells to repair treatment‐related lesions and contributing to treatment resistance." (PMID 37491696, 2023).
glioma (12 papers, 2011 to 2025). A benign or malignant brain and spinal cord tumor that arises from glial cells (astrocytes, oligodendrocytes, ependymal cells). "MPG overexpression was previously associated with cellular sensitisation to alkylation: studies involving breast, glioma, and ovarian cancer cell lines reported that MPG overexpression conferred sensitivity to alkylating agents, such as TMZ." (PMID 28903334, 2017). "The results revealed that the expression of MGMT and MPG in most patient-derived gliomas cells was lower than detected in control (T98G) cells." (PMID 33335215, 2020). "With that in mind, we evaluated for the first time the degree of resistance to TMZ treatment in 18 patient-derived glioma cells and its association with MGMT and MPG mRNA levels." (PMID 33335215, 2020). "Inhibition of Rad51 and MPG has been described to sensitize glioma cells to other agents, such as TMZ, a drug that is commonly used to treat brain tumors, opening new therapeutic combination options." (PMID 31036068, 2019). "Findings from that investigation showed that the expressed levels of the MPG gene increase as tumors progress from grade I to grade IV gliomas according to the results of real-time PCR, and that the survival rate of MPG-positive patients was significantly lower than that of MPG-negative patients." (PMID 33335215, 2020). "MPG has been described as an unfavorable independent prognostic factor for glioma patients and MPG gene and protein expression increase from low‐ to high‐grade gliomas." (PMID 29949238, 2018). "Most interestingly, we found that 90% of cell cultures showed high expression of MPG with values above 0.4–0.5, whereas mRNA levels of MGMT were significantly different for each glioma primary culture." (PMID 33335215, 2020). "We observed the inhibition of proteins that play a main role in double strand break repair, such as Rad51, MPG and proteins that are part of the MRN complex, in pediatric glioma cells infected with Delta-24-RGD." (PMID 31036068, 2019). "Glioma patients undergoing TMZ treatment with low MPG levels, possibly due to MPG promoter methylation, have a better outcome compared to those with high MPG expression." (PMID 29949238, 2018). "Aberrant expression of AURKB, MPG and SNCB has been observed in cancers of neuronal cell types - gliomas, astrocytomas and medulloblastomas, respectively." (PMID 22087225, 2011). "Additionally, preclinical and clinical studies are required to provide convincing evidence showing that inhibition of MPG alone or in combination with the MGMT inactivation enhances TMZ activity and produces a clinical benefit for patients with gliomas." (PMID 33335215, 2020).
breast carcinoma (6 papers, 2009 to 2024). "The loss of MPG expression in breast cancer cells could potentially enhance the effectiveness of alkylating agents such as those used in chemotherapy by limiting DNA repair and enhancing apoptosis." (PMID 20064251, 2010). "MPG has been identified as a highly expressed gene in human breast cancer tumors." (PMID 39764614, 2024). "In addition, an overexpressed MPG gene has been reported to sensitize human breast-cancer cells and ovarian-cancer cells to a chemotherapeutic agent." (PMID 37298600, 2023). "Our laboratory identified oxidative stress (SOD1, Ape1/Ref-1, Trx, TrxR and PDI) and DNA repair (NM23-H1, MPG and Ape1/Ref-1) proteins associated with the DNA-bound ERα and showed that each of these proteins influences estrogen-responsive gene expression in MCF-7 human breast cancer cells." (PMID 20064251, 2010). "In this current study, we hypothesize that the repair of DNA damage induced by PAC in both breast-cancer cell lines by the BER pathway starts with the recognition and removal of the damaged bases by N-methylpurine DNA glycosylase." (PMID 37298600, 2023). "It has been shown that N-methylpurine DNA glycosylase (MPG) and Polβ expression predict the sensitivity to the alkylating cancer drug temozolomide and that Polβ-dependent 5’dRP lyase activity is the rate-limiting step in BER in breast cancer cells." (PMID 29156686, 2017).
colorectal cancer (4 papers, 2006 to 2023). A primary or metastatic malignant neoplasm that affects the colon or rectum. "Interestingly, ZEB1 was shown to be induced in chronically inflamed intestinal mucosa and to promote intestinal inflammation and colitis-associated colorectal cancers through the repression of the N-methyl-purine glycosylase MPG-encoding gene." (PMID 36765930, 2023). "We propose that it would be clinically important to assess MPG expression levels in sporadic colorectal cancer cases." (PMID 28903334, 2017). "The proteins DDX17, MPG and PAK1 have been linked to colorectal cancer." (PMID 22087225, 2011).
lung carcinoma (4 papers, 2020 to 2024). "It has been also reported that a personal low baseline DNA repair score, composed of the BER-associated enzymatic activities of APEX1, MPG and OGG1 (all of which act primarily on oxidative DNA damage) consists of a strong risk factor for lung cancer." (PMID 35740268, 2022). "The alkyl-purine DNA glycosylase (MPG/AAG/ANPG) initiates aberrant BER by removing regular purines from nondamaged DNA, and the increased level of MPG is associated with risk of lung cancer." (PMID 33553154, 2020). "The results presented here indicate that a personal low baseline DNA Repair score, composed of the enzymatic activities of OGG1, MPG, and APE1, is a strong risk factor for lung cancer." (PMID 32064457, 2020). "To examine whether a low DNA Repair score is associated with lung cancer risk in the United Kingdom, we conducted a case-control study with 150 non–small cell lung cancer case patients and 143 control individuals for whom we tested the enzymatic activities for OGG1, MPG, and APE1 in PBMC." (PMID 32064457, 2020).
colitis (3 papers, 2020 to 2023). Inflammation of the colon. "Zeb1-deficient mice were partially protected from experimental colitis and, in a model of inflammatory CRC, they developed fewer tumors and exhibited lower levels of DNA damage (8-oxo-dG) and higher expression of MPG encoding DNA-3-methyladenine glycosylase." (PMID 32252452, 2020).
ischemic stroke (2 papers, 2020 to 2025). A stroke disorder caused by obstruction of blood flow to the brain, due to thrombotic (local blood clot formation) or embolic (due to a blood clot or other material traveling from another site) event. "Therefore, we hypothesized that the MPG gene is associated with ischemic stroke prevalence and prognosis." (PMID 33202874, 2020). "Furthermore, the MPG rs256262 CT+TT was associated with increased platelet levels compared to the platelet levels with the MPG rs256262 CC genotype (CC vs. CT+TT; P = 0.022) in ischemic stroke patients." (PMID 33202874, 2020). "Although we did not identify the cause of low mortality in SVD patients (with or without hypertension) with the MPG rs2562162 dominant model, our analysis did show that the MPG rs2562162 polymorphism was significantly associated with the rate of ischemic stroke patient survival." (PMID 33202874, 2020). "Nitrogen permease regulator-like 3 (NPRL3) and N-methylpurine DNA glycosylase (MPG) genotypes and haplotypes may also offer clinically relevant biomarkers for the development, prevention, prognosis, and management of ischemic stroke." (PMID 41009953, 2025). "Additional studies such as the replication study are needed to confirm that the NPRL3 and MPG genes play a crucial role in ischemic stroke pathogenesis and to provide more evidence that the regulation of NPRL3 and MPG expression or activation can be used as a tool to prevent ischemic stroke." (PMID 33202874, 2020).
nephritis (2 papers, 2014 to 2016). Inflammation of renal tissue. "We also reported novel autoantigens by protein array screening as being associated with active nephritis and hypocomplementemia: APEX nuclease 1 (APEX), N-methylpurine-DNA glycosylase (MPG), and CAP-GLY domain containing linker protein family member 4 (CLIP4)." (PMID 31557984, 2016). "Autoreactive IgE’s to APEX, MPG, and CLIP4 also showed a highly significant association with hypocomplementemia and with active nephritis." (PMID 24587356, 2014).
breast tumors (1 paper, 2013). "RNA-Seq analysis indicated that 2 isoforms of the MPG (NM_001015052 and NM_001015054) were expressed in breast tumors." (PMID 24223926, 2013).
colon cancer (1 paper, 2017). "ATP levels were significantly reduced 1 h after 5-FU treatment (2.5μM) in MPG-overexpressing colon cancer cells, but the basal increase resulting from MPG overexpression meant 5-FU-treated cells still maintained higher ATP levels than control." (PMID 28903334, 2017). "MPG overexpression was previously reported in some types of neoplasias, including CRC, however, to our knowledge, MPG-dependent sensitization to 5-FU in colon cancer cells has not been previously reported." (PMID 28903334, 2017). "we were able to show that MPG overexpression results in increased sensitization to 5-FU in colon cancer cells, despite 5-FU not being a known MPG substrate." (PMID 28903334, 2017). "Imbalancing BER by overexpression of MPG, but not XRCC1, sensitises MMR-deficient colon cancer cells to 5-FU and TMZ and leads to ATP depletion and lactate accumulation." (PMID 28903334, 2017).
malignant glioma (1 paper, 2020). A grade III or grade IV glioma arising from the central nervous system. "We further suggest that the analysis of expression level of both MGMT and MPG in tumor samples after surgery or biopsy might be used to predict effectiveness of TMZ treatment in malignant glioma patients." (PMID 33335215, 2020).
pertussis (1 paper, 2023). A contagious bacterial respiratory infection caused by Bordetella pertussis. "BPZE1 was prepared by the knockout of the B. pertussis gene that encodes for skin necrosis toxin and replacement of the A mpG gene of pertussis by the A mpG gene of Escherichia coli, thus greatly reducing tracheal cytotoxin production." (PMID 37242993, 2023).
prostate carcinoma (1 paper, 2013). A carcinoma that arises from epithelial cells of the prostate gland. "Additionally, prostate cancer cells were treated with anti-β2-M Ab (10 μg/ml) for 24 h and the protein levels of DNA repair enzymes MPG and NUDT1 were examined." (PMID 23874600, 2013).
renal fibrosis (1 paper, 2020). A final common manifestation of a wide variety of chronic kidney diseases characterized by glomerulosclerosis and tubulointerstitial fibrosis. "Further, rats that were fed the HP-HCa2+ diet expressed lower levels of four key markers of renal damage and fibrosis (NGAL, COL1A1, COL6A2, and MPG) and exhibited decreased renal fibrosis revealed by Masson’s trichrome staining to detect collagen." (PMID 32271147, 2020).
cancer (17 papers, 2010 to 2025). A tumor composed of atypical neoplastic, often pleomorphic cells that invade other tissues. "It has been noted that an elevated expression of MPG in certain types of cancer cells confers higher sensitivity to alkylation agents because MPG-induced apurinic/apyrimidinic (AP) sites trigger more strand breaks." (PMID 37298600, 2023). "Targeting DNA repair molecules, such as DNA polymerase β (Pol β), MGMT and N-methylpurine-DNA glycosylase (MPG), increased the sensitivity of cancer cells to alkylating chemotherapeutics." (PMID 33918653, 2021). "Supporting this, elimination of N-Methylpurine DNA glycosylase (MPG) or inhibition of APE1 has been shown to increase sensitivity of cancer cells to alkylating chemotherapeutics." (PMID 32850380, 2020). "The human N-methylpurine DNA glycosylase (MPG) orthologue is overexpressed in several types of cancers." (PMID 32762689, 2020). "Conversely, BER imbalance by overexpression of an initiating glycosylase such as MPG sensitizes cancer cells to chemotherapeutic alkylating drugs." (PMID 28903334, 2017). "Specifically, the enzyme of interest in the present study, MPG, has been shown to be important in preventing cancer in a mouse model of inflammation-mediated colon carcinogenesis." (PMID 25081213, 2014). "Its deregulation may thus alter the functionality of cancer‐relevant nuclear proteins, such as the base excision repair (BER) enzyme N‐methylpurine DNA glycosylase (MPG), which has been associated with treatment resistance in GBM." (PMID 37491696, 2023). "Furthermore, overexpression of oxidative stress (SOD1, Ape1/Ref-1, Trx, and PDI) and DNA repair (MPG and Ape1/Ref-1) proteins has been shown to provide resistance to chemotherapeutic agents and impede cancer treatment." (PMID 20064251, 2010). "MPG overexpression could increase 5-FU therapeutic efficacy so the identification of MPG overexpressing tumours could indicate a better response to therapy in these cancer patients." (PMID 28903334, 2017). "ECM secretion by cancer cells in low-adhesion environments has been suggested previously; for example, increased expression of SPARC, MPG and SPON2 has been reported in circulating tumour cells from patients." (PMID 36546396, 2022). "Furthermore, the human orthologue N-methylpurine DNA glycosylase (MPG) has been shown to negatively regulate cell cycle arrest and is overexpressed in several types of cancers." (PMID 27911910, 2016).
tumor (17 papers, 2015 to 2025). "Within the irradiated group, we found downregulation of UNG, FEN1, PARP3, POLD, NTLH1, ERCC1 and MPG which are linked to increased DSBs, sensitivity to alkylating agents, impaired tumor growth and reduced EMT, DSB repair and mitotic progression." (PMID 34680264, 2021). "Several genes particularly CXCL14, COX6C, CRISP3, and MPG with high expression levels in these tumor regions were identified, while healthy cells exhibited few significant genes, with only MALAT1 observed." (PMID 39764614, 2024). "In addition, because BER imbalance may modulate cell survival in a replication-dependent manner, we assessed whether overexpression of BER proteins, notably MPG, was associated with higher tumour proliferation by examining proliferating cell nuclear antigen (PCNA) expression in our samples." (PMID 28903334, 2017). "However, immunohistochemical evaluation of MPG in the treatment naïve GBM also identified tumors with both nuclear and cytoplasmic MPG expression patterns that displayed a wide range of HTATIP2 expression reflecting tumor heterogeneity." (PMID 37491696, 2023). "However, tumours with reduced MMR gene expression also displayed low MPG, OGG1 and PARP1 expression." (PMID 28903334, 2017). "Next, we assessed protein expression levels by immunohistochemistry for MLH1, MPG, FEN1, Polβ and XRCC1 in tumour vs. healthy tissue of this patient cohort." (PMID 28903334, 2017). "Higher protein expression levels in tumour tissue were identified for MLH1, MPG, Polβ and XRCC1, respectively, in 79%, 59%, 56% and 57% of all cases." (PMID 28903334, 2017). "The DNA repair activity of multiple lesion-specific DNA glycosylases, such as MPG, SMUG1, UNG, NTH1, NEIL1 and OGG1 could be readily detected in lysates from human tumor cells (LN428, U2OS and K562 cell lines) and normal cells (PBMCs)." (PMID 30167090, 2018).
MPG also shares sentences with these, for which no sentence is quoted: ovarian carcinoma (4 papers); astrocytoma (2); infection (2); Blindness (1); brain tumors (1); C. perfringens infection (1); chronic renal failure (1); colon (1); colorectal (1); colorectal adenocarcinoma (1); colorectal tumours (1); dyslipidemia (1); hepatoblastoma (1); Hypertension (1); inflammation (1); insomnia (1); medulloblastoma (1); melanoma (1); Obesity (1); retinal degeneration (1); rheumatoid arthritis (1); Stroke (1).